IGF2BP3 (insulin like growth factor 2 mRNA binding protein 3)
Diseases named in the same sentence as IGF2BP3 in open-access papers (continued):
Sharing a sentence is not in itself a finding about the gene and the disease.
cancer (continued). "Recent accumulating evidence has demonstrated that IGF2BP3 is a potential oncogene in many types of cancers." (PMID 36313631, 2022). "Recently, a growing body of research has suggested that long noncoding RNAs interact with IGF2BP3 and have substantial effects on cancer progression." (PMID 35676262, 2022). "IGF2BP3 is a potential oncogene and is significantly upregulated in a variety of human cancer types." (PMID 35047058, 2022). "With its recently reported function as an m6A reader, many studies have sought to understand how RNA modifications in turn regulate the mechanism of IGF2BP3 in both development and cancer." (PMID 36307883, 2022). "By searching the GSCALite database, we found that the expressions of many m6A methylation regulators (especially IGF2BP1, IGF2BP2, and IGF2BP3) were changed across multiple cancer types." (PMID 35003212, 2021). "Similar to IGF2BP1, IGF2BP3 expression correlates with a poor prognosis and tumor aggressiveness in several cancers including gastrointestinal cancers, lung cancer, and melanoma." (PMID 34203267, 2021). "IGF2BP3 is a member of the IGF2 mRNA binding protein family—also known as the m6A binding protein—which exerts its biological functions in various human cancers." (PMID 34802443, 2021). "Together with IGF2BP1, IGF2BP3 facilitates invadopodia formation and cancer metastasis by preventing the degradation of the CD44 mRNA." (PMID 34203267, 2021). "IGF2BP3 is an oncofetal protein that is normally expressed in fetal/embryonic tissues, but is often aberrantly re-expressed in malignant tumors." (PMID 33805930, 2021). "IGF2BP3 has been found to be highly expressed and to be a potential oncogenic factor in plenty of cancers including SC." (PMID 34621671, 2021). "Collectively, IGF2BP3 functions as a fine-tuner regulating the expression of genes related to cancer progression and metastasis." (PMID 34329193, 2021). "We found that the most significant difference between cancer and paracancerous m6A regulatory factor is IGF2BP3." (PMID 34737950, 2021). "Subsequently, qRT-PCR was applied to investigate the IGF2BP3 expression in LSCC, and the detection results were generally consistent with the TCGA database, i.e., IGF2BP3 in LSCC was significantly upregulated compared to healthy tissues adjacent to cancer." (PMID 33637103, 2021). "Being a significant RBP, IGF2BP3 is involved in the process of mRNA metabolism and contributes to the cell proliferation and invasion in various cancers." (PMID 32984260, 2020). "On the other hand, based on KEGG annotation, we find that the spliceosome pathway ranks first and IGF2BP3 targets also involved in the processes like focal adhesion, proteoglycans in cancer, pathways in cancer, and RNA transport." (PMID 32984260, 2020). "It has also been found that IGF2BP3 can stabilize TRIM25, and both TRIM25 and IGF2BP3 play an essential role in cancer cell proliferation." (PMID 32648571, 2020). "At the cancer type level, some of the perturbations we identified, such as IGF2BP3 and DKK1-MDFI, have already been suggested to be KIRP biomarkers." (PMID 32152446, 2020). "As evidence has shown important roles of IGF2BP1, IGF2BP2, and IGF2BP3 in cancer, we next explored their expression in various types of cancer." (PMID 33575259, 2020). "Herein, we used iRIP-seq to uncover the mysteries of interactions between IGF2BP3 and RNA in human cancer cell line." (PMID 32984260, 2020). "We profiled control-transfected and IGF2BP3-depleted A673 EWS cells for genes encoding chemokine receptors and ligands using the RT2 Profiler Cancer Inflammation and Immunity Crosstalk PCR Array." (PMID 32719743, 2020). "Current research on the IGF2BP family suggests that IGF2BP3 is undoubtedly an oncofetal protein that plays an essential role in cancers from onset." (PMID 32760394, 2020). "Insulin‐like growth factor‐2 messenger RNA‐binding protein 3 (IGF2BP3) has been reported to contribute to tumorigenesis in several human cancers." (PMID 33094561, 2020).
cancer (continued). "Previous studies indicated that IGF2BP3 involved in the growth, chemo‐resistance and progression in many cancers." (PMID 33094561, 2020). "Subsequently, we investigated expression of IGF2BP3 in pan-cancer based on TCGA databases and Oncomine databases respectively." (PMID 32993738, 2020). "So we first studied the expression level of IGF2BP3 in different cancer types through the Oncomine database." (PMID 32984260, 2020). "Among these proteins, IGF2BP3 has been reported to act as a critical regulatory factor in certain cancers." (PMID 32760394, 2020). "In contrast to evidence in normal embryonic tissues, IGF2BP3 promotes IGF2 mRNA translation in cancer cells by binding its 3′-UTR, leading to the increased activation of IGF signaling." (PMID 32010687, 2019). "Recently, studies of IGF2BP3 are rapidly increasing, mostly with a focus on its involvement in the pathogenesis of a broad range of cancers." (PMID 32083017, 2019). "The authors are grateful to Giorgio Durante (Laboratory of Experimental Oncology, IRCCS Istituto Ortopedico Rizzoli, Bologna, Italy) for his support with the analysis of IGF2BP3 gene expression across human tissue and cancer types." (PMID 32010687, 2019). "Although there is clear support showing that IGF2BP3 plays a direct role in tumorigenesis and cancer progression, the mechanisms by which IGF2BP3 elicits its effects are incompletely understood." (PMID 32010687, 2019). "This review focuses on IGF2BP3 and its role in human cancer, highlighting the contradictions and discrepancies related to its still poorly understood mechanisms of action and the potential of this protein as diagnostic, prognostic and therapeutic biomarker." (PMID 32010687, 2019). "At the experimental level, IGF2BP3 sustains cancer cell growth and proliferation while putatively inhibiting apoptosis." (PMID 32010687, 2019). "More recently, a large-scale sequencing analysis of datasets of 15 cancer types from The Cancer Genome Atlas (TCGA) confirmed these data, showing an inverse correlation between the DNA methylation status of the IGF2BP3 promoter and IGF2BP3 mRNA expression." (PMID 32010687, 2019). "Of those, the highly conserved family of insulin-like growth factor 2 mRNA-binding proteins (IGF2BPs), which includes the paralogs IGF2BP1, IGF2BP2, and IGF2BP3, primarily play oncogenic roles in cancer." (PMID 32010687, 2019). "IGF2BP3 has been reported to be involved in the progression of various cancers, including those in the pancreas, colon or rectum, lungs, and ovaries." (PMID 32083017, 2019). "Based on its absence in normal tissues, with very few exceptions, IGF2BP3 represents a putative valuable and specific target for cancer therapy." (PMID 32010687, 2019). "IGF2BP3 is synthesized de novo in cancer, where it promotes proliferation, drug resistance, and metastasis via both IGF2-dependent and IGF2-independent mechanisms." (PMID 29731738, 2018). "IGF2BP1 and IGF2BP3 have been reported in multiple types of cancers as stability regulators of multiple mRNAs." (PMID 29679004, 2018). "IGF2BP3 has been reported to participate in tumorigenicity in numerous kinds of cancers and its overexpression in tumorous tissues makes it a promising biomarker for diagnosis or prognosis accordingly." (PMID 28399871, 2017). "Subsequent studies found that IGF2BP3 functions as an oncofetal protein and is up-regulated in a variety of cancers such as breast cancer, hepatocellular carcinoma, etc." (PMID 29212181, 2017). "The dysregulation of IGF2BP3 expression in cancer tissue suggests a potential role for this molecule in tumorigenesis." (PMID 29212181, 2017). "Multiple studies have evaluated the expression of IGF2BP proteins (mainly IGF2BP3) in cancer and have consistently correlated IGF2BP3 expression with the subsequent development of recurrence or metastases in localized cancer and worse clinical outcomes." (PMID 28798901, 2017).
cancer (continued). "Consistent with previous studies, positive staining of IGF2BP3 was observed both in nucleus and cytoplasm in cancer tissues." (PMID 29212181, 2017). "The bioinformatics analysis by cBioPortal and GO database showed that the expression of IGF2BP3 in cancer tissues was highly correlated with 395 genes, which mainly participated in biological processes of cell cycle and cell proliferation." (PMID 29212181, 2017). "The IGF2 mRNA binding protein family (IGF2BPs) is comprised of three members: IGF2BP1, IGF2BP2, and IGF2BP3, which are bona fide oncofetal proteins involved in various human cancers." (PMID 26547929, 2015). "Because IGF2BP3 is undetectable in adult human tissues except the testis, and increased IGF2BP3 expression has been noted in several cancers, it is considered a cancer testis (CT) protein." (PMID 26244168, 2015). "IGF2 mRNA binding protein 3 (IGF2BP3) is an mRNA binding protein and cancer testis protein that regulates the translation of IGF2." (PMID 26244168, 2015). "Overexpression of IGF2BP3 has been noted in numerous cancers including esophageal, lung, prostatic, gastric, pancreatic, hepatocellular and colorectal malignancies as well as sarcoma and melanoma." (PMID 26244168, 2015). "Expression of IGF2BP family members has been implicated in various cancers; however, the vast majority of reports consider exclusively IGF2BP1 and IGF2BP3." (PMID 23069990, 2013). "Despite controversial observations regarding a potential involvement of IGF2BPs in metastasis, IGF2BP1 and IGF2BP3 emerge as potent modulators of cell migration during development and in cancer." (PMID 23069990, 2013). "However, abnormal expression of IGF2BP2 and reactivation of IGF2BP1 and IGF2BP3 are frequently observed during cancer progression." (PMID 41049442, 2025). "The analysis revealed significantly elevated expression of IGF2BP3 in all four cancer types." (PMID 40765570, 2025). "Furthermore, some genes (e.g., FXR2, METTL16) generally show copy number losses in pan-cancer, while some (e.g., IGF2BP3, YTHDF1) primarily exhibit copy number amplifications." (PMID 40867324, 2025). "circARID1A binds to IGF2BP3 in GC and promotes cancer proliferation." (PMID 40418151, 2025). "Our findings offer insights that could guide future research into the role of IGF2BP3 in these cancers." (PMID 40765570, 2025). "Initially, the expression profile of IGF2BP3 across various cancers was examined." (PMID 40765570, 2025). "IGF2BP3 may help stabilize the mRNAs stability of target genes via its m6A modification site, thereby promoting cancer development and progression." (PMID 41589308, 2025). "Finally, we validated the high expression of IGF2BP3 across multiple cancers using data from the TCGA pan-cancer dataset." (PMID 40083693, 2025). "Initial analysis revealed that IGF2BP3 expression in gastrointestinal cancers exceeded the median expression levels observed across a broad range of cancers, laying the groundwork for further investigation into its diagnostic and prognostic significance in gastrointestinal cancers." (PMID 40765570, 2025). "Research has shown that IGF2BP3 regulates cancer progression by interacting with noncoding RNAs." (PMID 40418151, 2025). "Additionally, bioinformatics databases were used to investigate the impact of IGF2BP3 on the diagnosis and prognosis of these cancers." (PMID 40765570, 2025). "circARID1A binds to IGF2BP3 to promote cancer proliferation." (PMID 40418151, 2025). "HnRNPA2B1 and IGF2BP3, as m6A reader proteins, may play key roles in the progression of various cancers." (PMID 40770637, 2025). "Notably, IGF2BP3 was found to significantly promote cancer progression and showed strong clinical relevance in both overall survival (OS) and progression-free survival (PFS) cohorts." (PMID 41589308, 2025). "Insulin-like growth factor 2 mRNA binding protein 3 is upregulated in several cancers." (PMID 40418151, 2025). "IGF2BP3 is a potential oncogene spanning multiple cancer types." (PMID 41589308, 2025).
cancer (continued). "Additionally, GSEA analysis identified a positive correlation between IGF2BP3 levels in BLCA and gene sets related to "ANGIOGENESIS" and "EPITHELIAL MESENCHYMAL TRANSITION" (EMT), both of which are associated with cancer metastasis." (PMID 38504159, 2024). "We also observed that IGF2BP3 could enhance the expression of CD44, which is a well-known biomarker of cancer stem cells that are typically associated with increased proliferation capacity." (PMID 38504159, 2024). "The m6A reader IGF2BP3 is upregulated in various cancer, including glioblastoma." (PMID 38167409, 2024). "The diverse attributes characterizing IGF2BP3, such as its widespread overexpression in various cancer types, its regulatory control over genes influencing cell growth, and its restricted presence in specific human organs, collectively position it as a prime candidate for cancer therapy." (PMID 38429265, 2024). "Previous studies have reported that IGF2BP3 is highly expressed in various types of cancer." (PMID 38358034, 2024). "Next, we evaluated the prognostic value of IGF2BP3 in pan-cancer." (PMID 38577615, 2024). "The role of BRB in the process of reducing the development of CRC by inhibiting the influence of the insulin-like growth factor 2 mRNA-binding protein 3 (IGF2BP3) factor, which is significantly involved in the development of numerous cancers, was also examined." (PMID 39125943, 2024). "We also performed active mRNA translation sequencing (ART-seq) to capture actively translating transcripts upon IGF2BP3 knockdown and validated the protein expression level changes of the representative targets in both HepG2 and other cancer cell lines." (PMID 39198433, 2024). "IGF2BP3 has been associated with worse survival in several cancer types, but has not been previously associated with high wGII." (PMID 38703764, 2024). "IGF2BP3, an RBP linked to several malignant tumours, can bind to circFNDC3B." (PMID 40809111, 2024). "Therefore, the snoRNAs’ potential influence on IGF2BP3′s activity as a mediator of mRNA transit to lamellipodia should be investigated for its potential impact on overall cancer aggressiveness and malignancy." (PMID 38474168, 2024). "This study highlighted the vibrant role of IGF2BP3 in cancer progression." (PMID 38328550, 2024). "Here the authors show that the binding of IGF2BP1-3, especially IGF2BP3, with m7G, could promote the degradation of m7G target transcripts in cancer cells." (PMID 39198433, 2024). "Additionally, TISIDB database demonstrated that spearman correlations between the expression level of IGF2BP3 and immunoinhibitors, immunostimulators, as well as MHCs among human cancers." (PMID 38577615, 2024). "The roles of IGF2BP3 in IFN response in other types of cancer need further investigation." (PMID 38448411, 2024). "In GC, IGF2BP3 acts as an oncogene that stimulates cancer cell proliferation and invasion." (PMID 40809111, 2024). "Certain cancer cells may possess higher abundances of mRNA internal m7G and thus be subjected to stronger IGF2BP3 regulation through m7G." (PMID 39198433, 2024). "In addition, we also analyzed IGF2BP3 expression, prognosis and immune modulation in pan-cancer, revealing the prognostic value of IGF2BP3 in a variety of tumors." (PMID 38577615, 2024). "Another principal finding of this study was the primary role of IGF2BP3 in cancer immunity." (PMID 36761737, 2023). "However, upon reviewing the literature, there is no existing study comprehensively evaluating the significance of IGF2BP3 in pan-cancer on the whole scale." (PMID 36761737, 2023). "We then explored the correlation between IGF2BP3 and the functional state in specific cancers." (PMID 36761737, 2023).
cancer (continued). "Besides, IGF2BP3 was involved in many cancer pathways and varied in different immune and molecular subtypes of cancers." (PMID 36761737, 2023). "Many of these genes are involved in the regulation of cell cycle, apoptosis, and proteostasis and have cancer-associated functions, suggesting that by regulating their stability or translation IGF2BP3 might contribute to cancer progression." (PMID 37582618, 2023). "Therefore, our results highlight the importance of the identification of IGF2BP3 targets in various cancers in order to reveal their role in tumorigenesis." (PMID 37582618, 2023). "Moreover, immunostimulatory factors and immunosuppressive factors were also tightly correlated with IGF2BP3 expression in TCGA pan-cancer." (PMID 36761737, 2023). "Many target RNAs are oncogenic proteins, and IGF2BP3 exerts an oncogenic function in cancer." (PMID 37877353, 2023). "According to previous studies, IGF2BP3 can be a valuable prognostic marker in human cancer." (PMID 36732736, 2023). "In each instance, IGF2BP3 may act to amplify a particular oncogenic program specific to the cancer type." (PMID 37760460, 2023). "Previous work characterizing the role of IGF2BP3 in other cancers may offer insight into a shared pathway." (PMID 37760460, 2023). "ROC curve and Survival curve in pan-cancer plotted by Kaplan-Meier estimate revealed that IGF2BP3 had a certain accuracy (AUC>0.7) in predicting 24 cancer types, especially had a strong predictive power (AUC>0.9) in predicting LAML, GBM, UCS, LUSC, STAD, OV, CHOL, and ESCA." (PMID 36761737, 2023). "Moreover, IGF2BP3 has also been shown to be overexpressed in different cancers and shown to promote cell growth and motility as well as regulating responses to anticancer treatments." (PMID 37059726, 2023). "This may represent one mechanism by which IGF2BP3 promotes cancer progression; however, we acknowledge the role of IGF2BP3 is likely multifaceted." (PMID 37760460, 2023). "Interestingly, the most significantly upregulated genes in Ppm1dT/+ AML (Zbed3, Runx3, Marcks, Extl3, Pcbp4, Igf2bp3, Plch1, and Gdf6) were previously associated with AML and cancer progression." (PMID 37709843, 2023). "Though several substrates of IGF2BP1 and IGF2BP3 are known in cancers, including ESCC, the downstream mRNAs regulated by IGF2BP2 are largely unknown." (PMID 37444412, 2023). "Besides its role as a newly reported m6A reader, IGF2BP3 has also been well-proven to function in cancer metabolism, immunity, angiogenesis, stemness, and differentiation." (PMID 36761737, 2023). "Also, in the current study, IGF2BP3 was found to significantly correlate with classic immune checkpoint in human cancers, which remained one of the most successful immunotherapy strategies for multiple cancers." (PMID 36761737, 2023). "Here, we performed comprehensive research on the roles of IGF2BP3 in human pan-cancer." (PMID 36761737, 2023). "Previous studies have indicated that IGF2BP3 plays an oncogenic role in colorectal, pancreatic, lung, and bladder cancers." (PMID 37663284, 2023). "Analysis of a pan-cancer project showed that IGF2BP3 was amplified in most human cancer types." (PMID 36732736, 2023). "Notably, IGF2BP3 has been identified as a potential oncogene involved in the progression of various cancers." (PMID 37663284, 2023). "IGF2BP3 has been found to play oncogenic roles in various cancers including GC, while the exact mechanism of IGF2BP3 is largely unknown." (PMID 35986300, 2022). "Moreover, it was found that the expression levels of METTL3 and IGF2BP3 were higher in cancer tissues than those in adjacent tissues." (PMID 36276112, 2022). "Furthermore, IGF2BP3-circRNA interactions have been found in other types of cancer such as hsa_circ_0003258-IGF2BP3, CDR1as-IGF2BP3 and hsa_circ_0000231-IGF2BP3." (PMID 35986300, 2022).